Y_RNA (Y RNA )
Gene: Miscellaneous RNA gene on chromosome 10 (37,303,000 to 37,303,109, reverse strand). Ensembl gene ENSG00000252621.
Homologues: Orthologues: chimpanzee Y_RNA (97% identical), macaque Y_RNA (87% identical), mouse Gm24203 (76% identical), mouse Gm23921 (73% identical), rat Y_RNA (70% identical), mouse Gm55767 (67% identical), rat Y_RNA (65% identical), mouse Gm26456 (64% identical), rat Y_RNA (64% identical), mouse Gm56480 (63% identical), mouse Gm26124 (62% identical), mouse Gm26438 (61% identical), and 3 more. Paralogues in human: Y_RNA (79% identical), Y_RNA (78% identical), RNY1P5 (77% identical), Y_RNA (77% identical), Y_RNA (76% identical), Y_RNA (75% identical), RNY1P1 (75% identical), RNY1 (74% identical), RNY1P6 (74% identical), Y_RNA (74% identical), Y_RNA (73% identical), Y_RNA (72% identical), and 92 more.